IFNG (interferon gamma)
Diseases named in the same sentence as IFNG in open-access papers (continued):
Sharing a sentence is not in itself a finding about the gene and the disease.
Cachexia (continued). "Our cachexia classification was validated by the increase of CIFs genes in the tumor of LM patients, such as LIF, IL6, IFNG, and CCL2." (PMID 36774484, 2023). "Indeed, differential gene expression analysis of CD8+ T cells showed significantly higher expression of genes representing activated state in cachexia patients, including GZMH, GZMA, NKG7, and IFNG." (PMID 36376273, 2022). "Interestingly, we noticed a specific increase of IFNG expression in CD8+ T cells and CD8+ γδ T cells in adipose tissues from cachexia patients." (PMID 36376273, 2022). "In addition, the recovered IFNG expression, which was presumably from activated CD8+ T cells, after macrophage depletion in the mouse cachexia model, also indicated a functional connection between macrophages and CD8+ cells in driving adipose catabolism." (PMID 36376273, 2022). "Taken together, this work demonstrates that different pro‐cachectic inducers (i.e. IL‐6 and IFNγ/TNFα) activate STAT3 signaling independently and that this signaling can collaborate with the NF‐κB pathway to induce cachexia through activation of target genes, like iNOS." (PMID 28264935, 2017).
Opportunistic infection (52 papers, 2011 to 2026). An infection that is caused by a pathogen that would generally not be able to cause an infection in a host with a normal immune system. "As a result, IFNγ alone or in combination with other cytokines has successfully been used together with ART against HIV-associated opportunistic infections." (PMID 24454311, 2014). "Neutralizing anti-interferon gamma autoantibodies (nAIGAs) play a pivotal role in the pathogenesis of adult-onset immunodeficiency (AOID), predisposing affected individuals to severe opportunistic infections." (PMID 41824412, 2026). "However, considering the important role of IFNγ in host defense against opportunistic infections (most importantly Mycobacterium tuberculosis), a basal level is needed to maintain a healthy balance." (PMID 38983847, 2024). "As even partial improvement in IFNγ signaling could effectively improve the control of opportunistic infections, autoantibody suppression and IFNγ signaling restorations have been explored in recent years." (PMID 37365453, 2023). "Anti-interferon-gamma autoantibody-associated immunodeficiency syndrome is a rare and underrecognized adult onset immunodeficiency syndrome associated with severe opportunistic infections such as disseminated nontuberculous mycobacterium." (PMID 36085248, 2022). "Recently a newly identified clinical syndrome of disseminated non-tuberculous mycobacterial diseases (with or without other opportunistic infections in adult patients who were previously healthy, has been recognized in association with an acquired autoantibody to interferon-gamma." (PMID 26011559, 2015). "IFNγ has been used as adjunctive immunotherapy with or without ART for the treatment of HIV-associated opportunistic infections such as cryptococcal meningitis, Pneumocystis carinii, Toxoplasma gondii, Candida albicans, Mycobacterium avium, and visceral leishmaniasis." (PMID 24454311, 2014).
Pleural effusion (51 papers, 2008 to 2025). The presence of an excessive amount of fluid in the pleural cavity. "Tuberculous pleural effusions are characterized by enhanced MAIT cells expressing IFNγ and TNFα compared to periphery and after stimulation with Bacillus Calmette-Guerin (BCG)." (PMID 35056035, 2022). "Of the 180 MTB-positive patients, 157 underwent interferon gamma release assays (IGRAs) within 1 month before and 1 month after the biopsy examination, including 8 pleural effusion samples and 149 whole-blood samples, of which 92.4% (145/157) were IGRA positive." (PMID 37154704, 2023). "The origin of foamy macrophages is attributed to the ensuing inflammatory response, with roles for interferon gamma (IFNγ), tumor necrosis factor alpha (TNFα), lipids in the pleural effusion and necrotic milieu being identified as relevant players across host species." (PMID 34603294, 2021). "For the early diagnosis of TP, biomarkers in pleural effusion such as adenosine deaminase and interferon-gamma have been shown to be helpful, but further investigations are needed for the application of nucleic acid amplification tests and interferon-gamma release assays." (PMID 21338482, 2011). "As a result, researchers have investigated various biomarkers in pleural effusion, such as adenosine deaminase (ADA) and interferon-gamma (IFN-γ)." (PMID 39445216, 2024). "To study the effect of IFNγ on the immunopeptidome of TNBC, we utilized MDA-MB-231, a metastatic breast adenocarcinoma cell line derived via pleural effusion." (PMID 33968037, 2021). "PMN-MDSCs in pleural effusion increased the levels of reactive oxygen species and suppressed the production of interferon-gamma from T cells following nonspecific stimulation." (PMID 38742106, 2024). "We quantified the expression of HGF, adenosine deaminase (ADA), and interferon gamma (IFN-γ) in pleural effusion (PE) in 97 TPE subjects and 116 non-TPE subjects using an enzyme-linked immunosorbent assay (ELISA) or a fully automatic biochemical analyzer." (PMID 37485530, 2023). "Moreover, some serum or pleural effusion biomarkers such as lactate dehydrogenase (LDH), erythrocyte sedimentation rate (ESR), and Interferon-gamma (IFN-γ) can also be used as auxiliary guide diagnosis in TPE but with limited sensitivity and specificity." (PMID 36820087, 2023). "These tests have recognized limitations in clinical practice, such as low sensitivity, lengthy delay, or invasiveness; as a result, multiple biomarkers in pleural effusion have been investigated, including adenosine deaminase (ADA) and interferon-gamma (IFN-γ)." (PMID 32571326, 2020). "In four of these patients, interleukin (IL)-23, IL-27, and interferon-gamma (IFN-γ) measurements were not performed since pleural effusion samples could not be collected because the effusion had been drained prior to the study." (PMID 31455239, 2019).
Thrombocytopenia (51 papers, 2006 to 2026). A reduction in the number of circulating thrombocytes. "However, thrombocytopenia is more often associated with increased phagocytosis of platelets in response to antibodies on their surfaces and/or because of macrophage activation by inflammatory cytokines such as macrophage colony-stimulating factor (M-CSF) and Interferon gamma (IFN-γ)." (PMID 26062684, 2015). "We have also observed some aspects of human disease, such as thrombocytopenia, liver damage, and increases of IFNγ and TNFα cytokine production when this animal model was infected with a laboratory adapted DENV-1 (Mochizuki strain)." (PMID 26415508, 2015). "Transient drop in platelet counts has been previously observed in a number of mouse models of DEN infection including AG129, ruling out the possibility that the lack of IFNγ signalling in these mice would impair the mechanism(s) involved in thrombocytopenia." (PMID 20436920, 2010).
endometriosis (50 papers, 2008 to 2025). The growth of functional endometrial tissue in anatomic sites outside the uterine body. "The summary of the results of two studies shows that the IFNγ a13 allele was positively associated with the risk of endometriosis." (PMID 39767772, 2024). "This study aimed to evaluate the percentage of NK cells and their subsets and their relationship with serum levels of vitamin D and interferon-gamma (IFN-γ) in women with endometriosis." (PMID 39355310, 2024). "One article showed that interleukins IL-2 and IL-27 work together to enhance the growth and invasion of endometriotic stromal cells by regulating the balance between IFNγ and IL-10 in the context of endometriosis." (PMID 39767772, 2024). "Evidence suggests that the sensitivity and specificity of measuring IFNγ in blood plasma for diagnosing endometriosis at any stage are 0.68 and 0.63, respectively." (PMID 39767772, 2024). "The Estrogen/ERβ axis suppresses IFNα and IFNγ signaling pathways in ectopic endometrial lesions to promote the progression of endometriosis." (PMID 36358904, 2022). "Supporting this scenario is that subjects with endometriosis have significantly higher serum levels of interleukin (IL)-6, monocyte chemotactic protein-1, and interferon-gamma as compared to control women." (PMID 19019211, 2008). "Furthermore, ERβ also suppresses the IFNα and IFNγ signaling pathways in the eutopic endometrium of mice with endometriosis, and mice with endometrium-specific ERβ overexpression mice are infertile." (PMID 36358904, 2022). "These may indicate that increased IFNγ may enhance the adhesive and invasive activity of the ectopic lesions to enhance endometriosis progression." (PMID 36358904, 2022). "In addition to type I IFN, the level of type II IFN (IFNγ) is significantly elevated in the peritoneal fluid of endometriosis patients compared with fluid from healthy women." (PMID 36358904, 2022). "In the peritoneal cavity of endometriosis patients, the immune cells are recruited and secrete excessive levels of proinflammatory cytokines (interleukin (IL)-1, IL-6, TNF, and IFNγ), which promote disease development and progression." (PMID 36358904, 2022). "The trends of increased levels of IL-16, IL-18, IL-1β and IFNγ were seen both in PM and PBMC in endometriosis patients." (PMID 35565370, 2022). "Distinct pathways that existed between stage I-II and stage III-IV endometriosis included: adipogenesis, PI3K AKT mTOR signalling, peroxisome, glycolysis, TGF beta signalling, heme metabolism, and interferon gamma response." (PMID 31941945, 2020). "In all patients with endometriosis, significantly elevated levels of IFNγ were found compared to those without the disease." (PMID 39767772, 2024). "We found elevated levels of HO-1 along with IL-10 and the pro-inflammatory cytokines (IL-1β, IL-16, IFNγ) in PM but not in PBMC from endometriosis patients." (PMID 35565370, 2022). "Type II IFN (IFNγ) fails to induce apoptosis in ectopic endometrial stromal cells, especially ovarian endometriotic cyst stromal cells, unlike in eutopic endometrial stromal cells with endometriosis and normal endometrial stromal cells." (PMID 36358904, 2022). "Therefore, the role of IFNγ is not clearly described in the pathogenesis of endometriosis due to the contractual observations." (PMID 36358904, 2022). "Interestingly, consistent with a mild inflammation status, common TH1 cell inflammatory chemokines were more likely to be elevated (IFNγ, IL-12, and IL-6), while other T cell attractants involved in TH2 promotion were decreased in endometriosis patients (TARC and 6Ckine, respectively)." (PMID 31333337, 2019).
liver cancer (50 papers, 2011 to 2025). An epithelial or non-epithelial malignant neoplasm that arises from the liver. "In summary, cytokine-armed DCPs improve tumor response to cisplatin and anti-PD-1 by eliciting IFNγ-producing T cells, decreasing tumor multiplicity and extending survival in two aggressive liver cancer models." (PMID 37996514, 2024). "Previous reports indicate that liver cancer tissues are characterized with a high expression level of PD-L1, CTLA4, lymphocyte activation gene 3, and other immunosuppressive molecules, which is negatively associated with the tumour infiltration of IFNγ+ T lymphocytes." (PMID 35574316, 2022). "In liver cancer, layilin marks exhausted CD8+ T cells that suppress interferon-gamma (IFNγ) production." (PMID 41404063, 2025). "For example, some studies have shown that low expression of IFNγ manifests as a high metastasis rate and high recurrence rate of liver cancer, and activating CD8 + T cells to release IFNγ reduces the expression level of SLC7A11 and inhibits the cellular uptake of cystine, causing ferroptosis." (PMID 38200525, 2024). "We treated liver cancer cell lines with regorafenib in the presence or absence of IFNγ, and evaluated the cell surface levels of HLA-I and B2M protein by flow cytometry." (PMID 34458148, 2021). "HighLAYN expression in liver cancer predicted a poorer overall survival and forced expression ofLAYN in CD8 T cells inhibited interferon gamma (IFN-γ) production, suggesting that it may inhibit CD8 T-cell effector functions." (PMID 32089832, 2020). "Using an immune-competent liver cancer model in which senescence triggers CD8 T cell-mediated tumor rejection, we show that senescence also remodels the cell-surface proteome to alter how tumor cells sense environmental factors, as exemplified by type II interferon (IFNγ)." (PMID 36302222, 2023). "However, MBP and IFNγ expression showed no significance in OS of liver cancer patients (data not shown)." (PMID 35011007, 2021). "In addition, SHP is significantly increased in the interferon γ (IFNγ)/CH11-resistant HepG2 cells, whereas no SHP is detected in the IFNγ/CH11-sensitive liver cancer SNU354 cells." (PMID 26504773, 2015). "In our study, we saw trending increases in PD-L1 expression in non-immune tumor cells without the STAT1 binding site necessary for IFNγ, corroborating a recent study that found that IFN increased PD-L1 expression on liver cancer cells and required IFN-independent NAMPT." (PMID 36900204, 2023).
macrophage activation syndrome (50 papers, 2014 to 2026). A complication of rheumatic disease that is caused by excessive activation and uncontrolled proliferation of T lymphocytes and well-differentiated macrophages. "Increased levels of IFNγ-induced chemokines such as CXCL9, CXCL10, and CXCL11 were found to be associated with sJIA complicating macrophage activation syndrome." (PMID 35268506, 2022). "IFNγ has been reported to be essential for alveolar macrophage-driven pulmonary inflammation in macrophage activation syndrome." (PMID 35268449, 2022). "A majority of patients with COVID-19 exhibit a predominant IL-1/IL-6 signature, but can evolve into an IL-18/IFNγ signature mimicking cytokine profiles observed in other inflammatory diseases such as macrophage activation syndrome (MAS)." (PMID 32699149, 2020). "The pathogenesis of SJIA is complex, with an autoinflammatory presentation involving proinflammatory cytokines such as interleukin (IL)-1 and Il-6, a risk of life-threatening macrophage activation syndrome (MAS) in some patients also involving other cytokines, such as interferon gamma and IL-18." (PMID 35268449, 2022). "The dysregulation of IL‐18 and IL‐18BP is significantly associated with immune‐mediated diseases, especially those where IFNγ plays a pathological role, such as macrophage activation syndrome (MAS)." (PMID 41532007, 2026). "As a result, infection in humans and in animal models leads to a macrophage activation syndrome (MAS) where severity is related to high serum levels of IFNγ, IL-10, IL-12, and ferritin." (PMID 29686681, 2018).
celiac disease (49 papers, 2005 to 2025). An autoimmune genetic disorder with an unknown pattern of inheritance that primarily affects the digestive tract. "More recently, TRAFD1 has been associated with celiac disease and defined as a novel master regulator, involved in the regulation of a set of genes enriched for two major pathways of immune activation, IFNγ signalling and antigen processing/presentation." (PMID 38694231, 2024). "IL1β levels are increased in celiac disease, and together with TNF and IFNG, it favours intestinal permeability, a characteristic feature of celiac disease." (PMID 37175481, 2023). "Hence, the increased concentrations of interferon-gamma and TNF-α, which control CGRP synthesis, may explain the association between migraine and celiac disease." (PMID 38731144, 2024). "In celiac disease, TRAFD1 was recognized as an upstream regulator of IFNg signaling and thereby activating cytotoxic T-cells, an important pathomechanism." (PMID 39794498, 2025). "We found, as in celiac disease, strong upregulation of IL-17 signaling and Th17 cell differentiation in EED including induction of IL21, IL6, IL17A IL17F, IL22, IFNG, IL21R, and IL2RA." (PMID 39300663, 2024). "This cell type was enriched in active celiac disease (ACD), perhaps in response to IFNγ." (PMID 40328997, 2025). "Similar to celiac disease, expression levels of GBP5, CXCL10, IFI27, and IFNG were increased in tissues of patients with no or low-grade intestinal injury." (PMID 36282455, 2023).
metabolic syndrome (49 papers, 2011 to 2026). A cluster of metabolic risk factors for CARDIOVASCULAR DISEASES and TYPE 2 DIABETES MELLITUS. "IL‐18 is a proinflammatory cytokine that plays a key role in promoting immune responses by inducing interferon‐gamma (IFN‐γ) production, and it is implicated in inflammation‐driven diseases, including autoimmune disorders, metabolic syndromes, and chronic inflammatory conditions." (PMID 40317574, 2025). "In contrast to the IL10 and IFNA genes, the present study demonstrates lower expression of IFNG in the groups composed by patients with dyslipidemia (G1, G2, and G3)." (PMID 28316372, 2017). "In addition, supplementation with açai pulp decreased the concentration of interferon-gamma (IFN-γ) in individuals with metabolic syndrome." (PMID 35245316, 2022). "Similarly, we found a negative correlation between the IFNG gene with glycemic and lipid profiles; furthermore, the patients with dyslipidemia (G1, G2, and G3) expressed lower IFNG mRNA levels than systemically healthy patients (G4 and G5)." (PMID 28316372, 2017). "In MS patients with metabolic syndrome treated with metformin, MBP-reactive cells secreting IFNg and IL17 were reduced, while Tregs were increased in number and regulatory function." (PMID 39684351, 2024). "In contrast, a clinical study in 25 subjects with metabolic syndrome showed intravenous vit C administration increased the expression of inflammatory-related genes such as TNF-α, Interleukin 4 (IL-4), and Interferon-gamma (IFN-γ) in the mononuclear cells." (PMID 35949307, 2022). "Patients with dyslipidemia demonstrated statistically higher expression of the IL10 and IFNA genes, while IFNG, IP10, IRF1, JAK1, and STAT3 were lower in comparison with nondyslipidemic patients." (PMID 28316372, 2017). "The carriers of the A/G genotype in the metabolic syndrome group had significantly higher levels of IFNγ than those in the group without this syndrome." (PMID 30383538, 2018). "Therefore, we have decided to search for the relationship between the TNFα gene polymorphisms and serum levels of proinflammatory cytokines (IL-1α, IL-1β, IL-6, TNFα, IFNγ) and CRP in women with metabolic syndrome." (PMID 30383538, 2018). "The opposite occurred with the IFNG gene, which was more highly expressed in the groups without dyslipidemia (G4 and G5) compared to G1, G2, and G3." (PMID 28316372, 2017). "By contrast, whereas the circulating levels of IFNγ, a cytokine that is released by Th1 lymphocytes, were not different between patients and controls, the anti-inflammatory cytokine IL-4, which Th2 lymphocytes mainly produce, was significantly lower in the circulation of metabolic syndrome patients." (PMID 31109070, 2019). "Similar to IFNG, the expressions of JAK1 and STAT3 were statistically lower in subjects with dyslipidemia (G1, G2, and G3), and significant negative correlations were found between these genes and lipid parameters." (PMID 28316372, 2017). "In the same way of IFNG, IRF1 was higher in patients without dyslipidemia." (PMID 28316372, 2017).